TNF (tumor necrosis factor)
Diseases named in the same sentence as TNF in open-access papers (continued):
Sharing a sentence is not in itself a finding about the gene and the disease.
Obesity (continued). "Obesity accompanies chronic systemic inflammation, characterized by pro-inflammatory cytokines including IL-6 and tumor necrosis factor-α (TNFα), which are also known to accelerate insulin resistance and other metabolic abnormalities of obesity." (PMID 25144367, 2014). "We also found that 4-1BB expression was upregulated on muscle cells by obesity-related factors, including palmitic acid, TNFα, and LPS, which promote skeletal muscle cell inflammation." (PMID 24453430, 2013). "TNF-α, which is increased in obesity, significantly reduced EfnB1 mRNA expression level, suggesting that this cytokine is one of factors accounting for the low expression of EFNB1 in obese adipose tissue." (PMID 24098442, 2013). "Tumor necrosis factor-α (TNF-α) is the best candidate connecting higher destructive periodontal disease in obesity or metabolic syndrome." (PMID 24068858, 2013). "Serum adiponectin has important anti-inflammatory effects in obesity that inhibits proinflammatory cytokines (TNF-a, IL-6, and nuclear factor-kB) and induces anti-inflammatory cytokines (IL-10 and IL-1 receptor antagonist)." (PMID 24454412, 2013). "Researchers also found that TNF signaling plays an important role in the insulin resistance of obesity." (PMID 24094242, 2013). "Obesity is a chronic inflammatory condition, which enhances the risk of CVD and is associated with various inflammatory cytokines (TNF-α and IL-6)." (PMID 24324381, 2013). "In obesity, high levels of tumor necrosis factor α (TNFα) stimulate lipolysis in adipocytes, leading to hyperlipidemia and insulin resistance." (PMID 23951179, 2013). "The increased circulating levels of TNF-α of both obese rodents and obese humans, suggest a possible link between obesity and tumorigenesis." (PMID 24106481, 2013). "Obesity results in a chronic inflammatory state, and adipose tissue releases proinflammatory cytokines such as TNF and IL-6." (PMID 27335818, 2013). "Studies on human and animal models in the 1990s indicated that adipocytes secrete TNF-α, and hence the excess of fat in obesity leads to a systemic chronic inflammation." (PMID 24068858, 2013). "In the Mexican adult population, serum levels of IL-12 show a strong relationship with systemic low-grade inflammation and obesity-related markers, including TNF-α, abdominal obesity, percentage of body fat, and high glucose and triglyceride levels." (PMID 23533314, 2013). "Activation of JNK, which is induced by various inflammatory stimuli including TNFα, is involved in the development of obesity-related insulin resistance." (PMID 24358263, 2013). "aP2 gene is central to the pathway that links obesity to insulin resistance, possibly by linking fatty acid metabolism to the expression of (tumor necrosis factor-α) TNF-α." (PMID 23555088, 2013). "It is thus plausible that the increased circulating levels of TNF-α in obesity contributes to the asthma exacerbations." (PMID 24204674, 2013). "The first indication for increased cytokine release in obesity was provided by the identification of increased expression of TNFα in the adipose tissue of obese mice in the early 1990s." (PMID 23819063, 2013). "Tumor necrosis factor α (TNFα) is one of the elevated inflammatory factors in obesity that is elevated and plays an important role in obesity-associated diseases." (PMID 23951179, 2013). "TNF-α-mediated pathway interference has shown protection in diet induced animal models of obesity and metabolic syndrome." (PMID 23762871, 2013). "Diet-induced obesity produces an elevation in colonic TNF-α giving rise to a number of alterations including the dysregulation of the Wnt signaling pathway, with an important involvement in colorectal cancer." (PMID 24106481, 2013). "Obesity elevates TNFα expression in adipose tissues and ceramide is elevated via hydrolysis of SM by SMases and SPT-mediated de novo synthesis." (PMID 23761785, 2013).
Obesity (continued). "TNF-α is also an important mediator of insulin resistance in obesity and diabetes through its ability to decrease the tyrosine kinase activity of the insulin receptor." (PMID 23431244, 2013). "Nonetheless, there is inadequate information on PBMC TNF-α production in obesity or the metabolic syndrome in adults." (PMID 23984304, 2013). "Several adipokines have been described in the literature as humoral factors mediating effects of adipocytes (and hence obesity) on various tissues of which TNFα is the most widely studied." (PMID 24288542, 2013). "Some evidence has been reported addressing a role for TNFα in obesity and insulin resistance; however, few studies have examined the effects of TNFα activity on cytokine or adipokine secretion in adipose tissue." (PMID 24204798, 2013). "The circulating levels of several adipocytokines, such as TNF-α, IL-6, MCP-1, leptin, and PAI-1, are elevated in obesity and are reduced with weight loss." (PMID 23690838, 2013). "Whole body deletion of TNF-α or its corresponding receptor TNF receptor 1 (TNFR1) gene partially protects mice from obesity-induced IR." (PMID 23675368, 2013). "It is now clear that TNF-α is involved in array of pathological conditions like obesity, congestive heart failure, inflammations, and insulin resistance, nevertheless the exact role and degree of its effects are still not clearly understood." (PMID 23762871, 2013). "Since the discovery that gene expression of the major inflammatory cytokine TNF-α is elevated in WAT in animal models of obesity, there have been many studies on its involvement in insulin resistance and its other actions." (PMID 24369466, 2013). "In this regard, obesity at the onset of treatment with TNF-α blockers leads to a reduction of the beneficial effect of these drugs on MS associated to RA." (PMID 23431244, 2013). "In adults, serum pro-inflammatory cytokines such as TNF-α and IL-6 are elevated in those with obesity and T2D relative to healthy controls." (PMID 23984304, 2013). "It was originally proposed that adipocytes were the principle source of raised TNFα levels in obesity, however, it is now well recognized that TNFα is abundantly produced by macrophages in the SVF." (PMID 23698162, 2013). "Thus, elevated TNF-α plasma levels are associated with abdominal obesity and an increased risk of myocardial infraction in men, while IL-6 circulating levels increase with obesity and are associated with increased risk for myocardial infarction and new onset type 2 diabetes." (PMID 23484124, 2013). "TNF-α is an important mediator of insulin resistance in obesity and diabetes through its ability to decrease the tyrosine kinase activity of the insulin receptor." (PMID 23533500, 2013). "It is noteworthy that several studies have indicated that the production of pro-inflammatory mediators, such as TNF-α regulate PTP1B overexpression in obesity on the models of in vivo and in vitro." (PMID 23612372, 2013). "As obesity per se is considered a subclinical inflammation, the increased levels of TNF-α and CRP in breast cancer cases in the present study are consistent with stress-induced inflammation among newly diagnosed breast cancer patients." (PMID 23374911, 2013). "These activated macrophages, along with adipocytes, produce several pro-inflammatory cytokines such as TNF-α and IL-6, resulting in numerous metabolic dysfunctions that accompany obesity, e.g., systemic inflammation and atherosclerosis." (PMID 24009719, 2013). "Obesity is accompanied by infiltration of proinflammatory macrophages into adipose tissue; these cells secrete inflammatory cytokines, such as TNFα, which generate insulin resistance by stimulating catabolic pathways." (PMID 24368730, 2013). "TNF-alpha, was then used as a positive control because of its reported over-expression in the obesity/hyperglycemic condition." (PMID 23894607, 2013). "It was reported that TNF is expressed in human adipocytes, and TNF level is positively correlated with obesity." (PMID 23533517, 2013).
Obesity (continued). "The mechanisms by which TNFα is increased during obesity were unclear until the findings published in 2003 that chronic inflammation observed in rodents and humans was characterized by the accumulation of macrophages into adipose tissue." (PMID 23964268, 2013). "Capsaicin also attenuates obesity-induced inflammatory responses by reducing TNF-α, IL-6, IL-8, and MCP-1 levels, while enhancing adiponectin levels, important for insulin response." (PMID 23698776, 2013). "This inflammation is characterized by increased serum concentrations of C-reactive protein (CRP), interleukin 6 (IL-6), IL-8, monocyte chemotactic protein-1 (MCP-1), and tumor necrosis factor alpha (TNFα) in patients and different animal models of obesity." (PMID 23819063, 2013). "We then examined the effects of obesity-related factors, including free fatty acids (e.g., palmitic acid), lipopolysaccharide (LPS), and cytokines (e.g., TNFα) on the expression of 4-1BB and 4-1BBL in C2C12 skeletal muscle cells." (PMID 24453430, 2013). "In obese rats, including diet-induced obesity rats, it has been repetitively shown that PVAT causes endothelial dysfunction via proinflammatory cytokines such as TNFα or monocyte chemotactic protein-1 as well as through oxidative stress." (PMID 23573411, 2013). "Diabetic women presented not only the expected increased glycemia and obesity (higher BMI and WC) when compared with the female control subjects, but also increased hsCRP, TNF-α, uric acid and VEGF, accompanied by reduced adiponectin." (PMID 23570342, 2013). "Psoriasis and obesity share similar mediators of inflammation, mainly tumor necrosis factor-α (TNF-α) and interleukin-6 (IL-6)." (PMID 24159327, 2013). "As a result, obesity is now recognized as a state of low-grade systemic inflammation characterized by high circulating levels of inflammatory molecules, such as TNF-α, IL-6, and C-reactive protein (CRP)." (PMID 24324381, 2013). "Taking into consideration that serum IFN-γ has been shown to increase during obesity, it is conceivable to expect a positive relationship among TNF-α, IL-12, and leptin in our study population." (PMID 23986664, 2013). "TNF-α is an inflammatory cytokine secreted by adipose tissue, with high concentrations of TNF-α being linked to obesity and insulin resistance." (PMID 24455726, 2013). "With respect to this, a recent report has shown that the improvement of insulin resistance in patients with RA undergoing anti-TNF-α therapy is impaired by the presence of obesity." (PMID 23431244, 2013). "To date, TNFα has focused the attention as a preponderant inflammatory cytokine with important implications both at local and systemic levels in obesity and related diseases." (PMID 24416031, 2013). "Tumor necrosis factor-α (TNF-α) is one of the main mediators of the inflammatory response in obesity and is expressed by infiltrating macrophages and adipocytes in the hypertrophic adipose tissue." (PMID 24454366, 2013). "Obesity contributes to metabolic dysfunction, including increases in circulating cytokines (IL-6, IL-1, and TNF), a decrease in protective factors, such as adiponectin, and communication between cells in inflammatory and metabolic diseases." (PMID 23533315, 2013). "Possible mechanisms of this obesity-induced renal damage are fat tissue-derived factors detrimental to renal function, such as tumor necrosis factor-α, interleukin-6 and plasminogen activator inhibitor-1." (PMID 24225117, 2013). "The increased expression of TNFα in adipose tissue was considered to be responsible for the development of obesity or diabetes due to the induction of insulin resistance through downregulation of insulin receptors and glucose transporters." (PMID 23819063, 2013). "These macrophages are activated in the obese state and secrete IL-6, IL-1β, TNF-α and other pro-inflammatory cytokines, which contribute to a low-grade state of chronic systemic inflammation in obesity." (PMID 24025484, 2013).
Obesity (continued). "Collectively, these findings suggest that obesity-related hyperleptinemia is accompanied by a low-grade inflammatory profile, characterized by increased circulating levels of TNF-α and IL-12, and reduced concentrations of IL-10." (PMID 23986664, 2013). "Hypertrophied adipocytes produce less of the anti-inflammatory adipokines including adiponectin and produce more pro-inflammatory cytokines such as TNF-α, contributing to the chronic inflammation seen with obesity." (PMID 23967184, 2013). "In obesity, cytokines like TNF-α are elevated in circulation and result in cardiovascular endothelial dysfunction, plaque formation and CVD." (PMID 23383064, 2013). "TNF-α works similarly and its receptors, which are located in most tissues, are upregulated with obesity." (PMID 23431467, 2013). "Supportively, genetic deficiency of either TNF-α or TNF-α receptor prevented overnutrition from inducing obesity or insulin resistance in mice." (PMID 22328600, 2012). "For example, central administration of TNF-α at low dose can mimic the effect of obesity-related inflammatory milieu to activate IKKβ/NF-κB proinflammatory pathways, furthering the development of overeating, energy expenditure decrease, and weight gain." (PMID 22328600, 2012). "TNF knockout or wildtype mice were fed for 11 weeks with a high carbohydrate diet (HCD) to induce modest obesity." (PMID 23125848, 2012). "Of note, we have shown that mast cells in the epididymal fat of diet-induced obese mice contain and secrete tumor necrosis factor-α (TNF-α), a proinflammatory cytokine implicated in the pathogenesis of obesity." (PMID 22313574, 2012). "Leptin can control the production and activation of pro-inflammatory cytokines such as IL-6 and TNF-α by macrophages, and is a key regulatory factor expressed in both zebrafish and mammalian obesity in lipid metabolism." (PMID 22947075, 2012). "In conclusion, TNF-α-308G/A and the GNB3 C825T polymorphisms are associated with obesity and AMI in the Taiwanese population." (PMID 22408428, 2012). "Elevated TNF-α mRNA expression in WAT usually correlates with massive obesity and insulin resistance." (PMID 23056223, 2012). "Increasing obesity will lead to increased production of adipocytokines like TNF-α, IL-6 that lead to perpetuating cycle of JNK, and NF-κB activation leading to worsening insulin resistance." (PMID 22792473, 2012). "Adiponectin and leptin proved to be significantly related to TNF-α in control group and obesity was also related to TNF-α, confirming data from the literature." (PMID 22547903, 2012). "Obesity induced by a HFD led to a decrease in cytokine TNF-α production by peritoneal macrophages stimulated with LPS compared to macrophages of SD-fed mice." (PMID 22844426, 2012). "Further studies looking at the specific mechanisms by which anti-TNFα therapy affects IR and the mechanisms by which obesity interacts in this process should be pursued." (PMID 22765047, 2012). "Together, these data suggest that TNF-α regulates the expression of both chemerin and adiponectin, but with opposite effects, in obesity-related inflammation." (PMID 22509348, 2012). "Several studies suggest that TNF-α is involved in obesity-related insulin resistance and that TNF-α is one of the most important mediators of inflammation." (PMID 23173608, 2012). "Once it was discovered that there is an increased expression of the proinflammatory cytokine (TNFα) in adipose tissue in obese mice, much research was focused and turned on the key roles of inflammatory mediators in obesity." (PMID 23091306, 2012). "Although TNFα has been proposed as a link between obesity and insulin resistance, the baseline blood glucose was unchanged by HCD in the TNF-WT and TNF−/− mice in our study." (PMID 23125848, 2012). "TNF-α has been considered as a key mediator of obesity-related insulin resistance because of its increased expression in obesity and its inhibitory effect on insulin receptor signaling." (PMID 22615828, 2012).
Obesity (continued). "Adipose tissue, which is infiltrated by monocytes and macrophages in obesity, secretes numerous soluble mediators including adipokines such as adiponectin or leptin and many classical cytokines such as TNF-α, interleukin (IL)-6, and IL-1 family members." (PMID 22531046, 2012). "Several studies have demonstrated that TNFα plays a role in mediating insulin resistance as a result of obesity." (PMID 23125848, 2012). "In obesity, most adipokines, including leptin, resistin and tumor necrosis factor alpha (TNFα), are overproduced and promote inflammation." (PMID 22947075, 2012). "Although a correlation between plasma concentrations of TNF and obesity are described in horses, the tissue primarily responsible for production of this inflammatory protein has not been identified." (PMID 26486919, 2012). "Expression and secretion of TNF-α increase with obesity and correlate positively with body mass index." (PMID 23173608, 2012). "In conclusion, unsaturated fatty acids can reproduce a number of the anti-inflammatory effects of TLR4 or TNF-α inhibition and, therefore, constitute an attractive nutritional approach to treat obesity." (PMID 22279596, 2012). "Obesity leads to pro-inflammatory milieu characterised by increased levels of TNF-α, IL-6, leptin, angio-tensinogen, plasminogen activation inhibitor-1 and decreased adip-onectin levels which promote endothelial functions." (PMID 22726248, 2012). "Inflammatory state of obesity is characterized by insulin resistance, increased serum concentrations of C-reactive protein, IL-6, IL-8, TNF-α, and so forth." (PMID 23091306, 2012). "Obesity-promoted HCC development was dependent on the production of the tumor-promoting cytokines IL-6 and TNF-α, which cause hepatic inflammation and activation of the oncogenic transcription factor STAT3." (PMID 22470194, 2012). "The unbalance between IL-6/TNF-α levels and IGF-I levels in the elderly directly accounts for the loss of fat-free mass suggesting that obesity and sarcopenia are highly inflammation dependent." (PMID 23091306, 2012). "Patients affected by insulin resistance present increased TNF-α levels and mice with a TNF-α deficiency are protected by the insulin resistance-induced obesity." (PMID 22701480, 2012). "In summary, TNF-α is related to obesity, glucose intolerance, type-2 diabetes mellitus, and GDM, and it is positively correlated with body mass index (BMI)." (PMID 22462002, 2012). "It down-regulated not only the level of blood glucose and plasma insulin but also the expression level of leptin and TNF-α mRNAs in white adipose tissue of the diabetes/obesity mouse KK-Ay." (PMID 23675258, 2012). "Both mammary gland involution and obesity have been demonstrated to result in the elevation of a variety of inflammatory regulators, such as IL-6 and TNF-α, among others." (PMID 22403677, 2012). "Obesity-related elevation in proinflammatory molecules, including tumor necrosis factor-α and interleukin-6 are also believed to contribute to the development of both DM and metabolic syndrome." (PMID 22898260, 2012). "The presence of TNFα in obesity has been reported to contribute towards the development of cardiac hypertrophy in cardiomyocytes." (PMID 23125848, 2012). "Whilst TNFα is necessary for the maintenance of glucose homeostasis, for the control of appetite to prevent obesity and for IPostC-induced cardioprotection, it can also lead to cardiac hypertrophy." (PMID 23125848, 2012). "Overproduction of TNF-α has been found in obesity, atherosclerosis, insulin resistance, and type II DM." (PMID 22234148, 2012). "In otherwise healthy individuals, obesity is a significant contributor to IR; obesity is a low-grade inflammatory condition and TNFα is also thought to be the link between obesity and insulin resistance." (PMID 22765047, 2012). "TNFα production is markedly increased in muscle and adipose tissue in obese humans and rodent models of obesity-diabetes, compared with tissues of lean individuals." (PMID 23125848, 2012).